BCL2 (BCL2 apoptosis regulator)
Diseases named in the same sentence as BCL2 in open-access papers (continued):
Sharing a sentence is not in itself a finding about the gene and the disease.
cancer (continued). "The radioresistance caused by overexpression of anti-apoptotic protein Bcl-2 known to frequently occur in human cancer was also considered by introducing the concept of the adaptive response in the DSMK model." (PMID 25426641, 2014). "The decreased expression of Bcl-2 and increased expression of Bax is associated with the response of cancer cell lines to anticancer compounds." (PMID 25009600, 2014). "When the study performed by Hyndman36 was omitted in dominant model, Bcl-2 -938 C>A polymorphism was associated with increased cancer susceptibility (OR = 1.15, 95%CI: 1.06–1.25, P = 0.001), and the heterogeneity was obviously reduced." (PMID 25430556, 2014). "Like in most cancers, elevated expression of anti-apoptotic Bcl-2 proteins such as Mcl-1, Bcl-2 and Bcl-Xl causes resistance to spontaneous or drug-induced apoptosis in MM." (PMID 25008202, 2014). "As for studies investigating the association between Bcl-2 -938C>A polymorphism and cancer susceptibility, studies were published between 2007 and 2014." (PMID 25430556, 2014). "As for studies evaluating the prognostic significance of Bcl-2 -938C>A polymorphism in cancer, studies were published between 2007 and 2013 and carried out in Japan, Korea, Sweden, China and Germany." (PMID 25430556, 2014). "Bcl-2 -938 C>A polymorphism was significantly associated with increased cancer risk in five genetic models." (PMID 25430556, 2014). "Recently, polymorphism in Bcl-2 gene, variant in promoter region -938 C>A (rs2279115), has been reported to be associated with cancer susceptibility and prognosis many times." (PMID 25430556, 2014). "The association between Bcl-2 -938C>A polymorphism and susceptibility and prognosis in cancer was carefully investigated." (PMID 25430556, 2014). "Analysis of Bcl-2 and survivin expression levels had been proved to be a useful diagnostic marker and an important source of prognostic information in cancer." (PMID 25002914, 2014). "Hazard ratios (HRs) were used to measure the association between Bcl-2 polymorphisms and cancer prognosis." (PMID 25430556, 2014). "The association between B-cell lymphoma 2 (Bcl-2) polymorphism and cancer is under debate and remains elusive." (PMID 25430556, 2014). "Fourteen studies evaluating the prognostic value of Bcl-2 -938 C>A polymorphism in cancer were included in our meta-analysis." (PMID 25430556, 2014). "Some authors presented similar results; others associated more frequent expression of Bcl-2 in cancer cells with better prognosis and longer survival." (PMID 24741635, 2014). "With respect to TRAIL signaling, it has been shown that type-II cancer cells can acquire resistance to TRAIL-induced apoptosis by loss of Bax82 or increased expression of Bcl-2,83 Bcl-xL84 or Mcl-185." (PMID 24948009, 2014). "A previous study indicated that, in addition to Bim, other BH3-only members of the Bcl-2 family, including Bcl-2-associated agonist of cell death and Bcl-2-associated X protein, are involved in casticin-induced cancer cell apoptosis." (PMID 25289048, 2014). "For most cancers, the over-expression of Bcl-2 protein associates with poor survival, uncontrolled progression and resistance to anticancer agents, making Bcl-2 family members promising anticancer drug targets." (PMID 23737957, 2013). "It has been shown that inhibition of antiapoptotic Bcl-2 proteins in various cancer entities, including CRC, causes a sensitization to anticancer drugs." (PMID 24098503, 2013). "Studies in cancer cells have indicated that BCL2 contributes to chemotherapy resistance, and the aberrant expression of BCL2 has been associated with drug resistance to commonly used anticancer agents." (PMID 24137412, 2013). "A frequent “hallmark” of cancer cells is decreased sensitivity to apoptotic signaling, for example, through overexpression of antiapoptotic genes such as Bcl2." (PMID 23653658, 2013).
cancer (continued). "Cancer cells acquire resistance to apoptosis by overexpression of antiapoptotic proteins (Bcl-2,IAPs, and FLIP) and/or by the downregulation or mutation of proapoptotic proteins (Bax, Apaf-1, caspase-8, and death receptors)." (PMID 24250626, 2013). "Bcl-2 is an intracytoplasmic and membrane-associated apoptosis suppressor, and its overexpression is closely associated with survival of malignant tumors, in particular their aggressive behavior and poor prognosis." (PMID 22654601, 2012). "Bcl-2-mediated, mitochondria associated cell survival pathway (intrinsic pathway) is one of the major pathways that are targeted for inducing apoptosis in cancer cells." (PMID 22974127, 2012). "BCN1 encodes Beclin1, which is differentially co-expressed with Bcl-2 in our ER+ driver-network and has a key role in autophagy, a mechanism used by cancer cells to survive under stressful conditions." (PMID 22343619, 2012). "Higher Bcl-2 to Bax ratios due to the overexpression of Bcl-2 or down-regulation of Bax expression are commonly found in cancers, which not only confers a survival advantage to the cancer cells but also causes resistance to chemo- and radio-therapies." (PMID 22754353, 2012). "Downstream of VEGF, B-cell lymphoma 2 (Bcl-2) is an anti-apoptotic regulator protein that has been implicated in a number of cancers including SCLC." (PMID 22363766, 2012). "Akt is known to enhance the intrinsic mitochondria-associated cell survival pathway in cancer cells via increased phosphorylation of Bad and enhanced expression of Bcl-2 and Bcl-xL." (PMID 22974127, 2012). "BCL-2 is thought to be involved in resistance to conventional cancer treatment and its increased expression has been implicated in a number of cancers." (PMID 22313995, 2012). "In this study, we used a gene silencing approach to knockdown Bcl-2 in Cr(VI)-transformed cells and studied its effects on cancer-associated properties including cell growth, apoptosis, invasion, colony formation, and angiogenesis." (PMID 22666341, 2012). "These cancer-associated target mRNAs were connected to this network mainly through the interaction with apoptosis and cell death genes such as BCL2, CASP9 and ELK1." (PMID 21595958, 2011). "It has been reported that the over-expression of BCL-2 in many cancers leads to the loss of leukocyte homeostasis and their resistance to normal apoptotic processes." (PMID 22132131, 2011). "Bcl-2 is the founding member of the Bcl-2 family of apoptosis regulator proteins encoded by the BCL2 gene, which has been supported a role for decreased apoptosis in the pathogenesis of cancer." (PMID 22003408, 2011). "Bcl-2 itself is an anti-death protein, and its over-expression has been linked to cancer development, metastatic growth, and chemotherapy resistance." (PMID 24281071, 2010). "Cells transfected by eIF4E-targeted asON decreased not only the level of the factor itself, but also that of other cancer- associated proteins, such as Bcl-2, survivin, cyclin D1, C-myc, and VEGF." (PMID 22649602, 2009). "As GSI1, MG132 induces G2/M arrest and apoptosis with loss of Bcl-2 expression, thus the therapeutic use of proteasome inhibitors are also being considered in cancer treatment." (PMID 19513078, 2009). "We found that increased expression of cytoplasmic caspase-8 and bcl-2 protein was strongly associated with low Fuhrman's grade of carcinomas (p = 0.019 and p = 0.041, respectively)." (PMID 19222834, 2009). "The imbalance of Bcl-2 family protein expressions can cause a variety of diseases (e.g. cancers), which further proves the crucial therapeutic role of Bcl-2 apoptotic switch." (PMID 18213378, 2008). "BCL2 is an antiapoptotic gene and increased expression is associated with poor responses to systemic treatment of cancer." (PMID 17242701, 2007).
cancer (continued). "The increased chance of developing BC and PC in individuals with either the BRCA1 or BRCA2 mutation is consistent with the increased bcl-2 caused by the elimination of PRB being partly responsible for the increased incidence of cancer." (PMID 17678531, 2007). "The association between expression of bcl-2, bcl-XL and bax with radioresistant cancer suggests a potential mechanism by which cancer cells avoid the destructive effects of radiotherapy." (PMID 15928664, 2005). "Baicalin also has shown direct effects on Bcl-2, another hallmark for initiating cancer cell death." (PMID 40046778, 2025). "The authors explain the increase in the level of lipid peroxidation by the fact that the resulting intracellular singlet oxygen attacks lipids in cancer cells and causes their peroxidation, and the increase in Bax and Bcl-2 gene expression is due to an attack of singlet oxygen on mitochondria." (PMID 41226774, 2025). "Their loss leads to the overexpression of BCL2, which promotes cancer cell survival." (PMID 40355604, 2025). "Since 2000 to present, Hanahan and Weinberg have described the family of BCL2 proteins as hallmark of cancer and as a therapeutic target with mimicking molecules such as ABT-199, approved in 2015 for hematological malignancies as monotherapy and combination therapy." (PMID 39836700, 2025). "In the present study, BCL-2 gene expression has increased significantly in the exosome group which is a double edge sword as besides the antiapoptotic properties which helped with the healing of the salivary gland, the increased BCL-2 levels have also been linked with different types of cancer." (PMID 40223864, 2025). "In this study, we identified several miRNAs that could have beneficial effects against cancer, such as one that potentially downregulates the BCL2 gene, which encodes an anti-apoptotic protein and is frequently overexpressed in various cancer types." (PMID 41440174, 2025). "However, overexpression of antiapoptotic proteins, particularly Bcl-2 and Bcl-xL, is commonly associated with cancer, as it enables cells to evade apoptosis, leading to unchecked proliferation." (PMID 40725141, 2025). "Previous studies have shown that hispidulin induces apoptosis through BAX activation, leading to mitochondrial membrane potential (MMP) loss and cytochrome c release, as well as an increased BAX/Bcl-2 ratio in multiple cancer cell lines, including CNE-2Z, SMMC7721, PANC-1, and HT29 cells." (PMID 40141371, 2025). "Under normal conditions, apoptosis allows for the elimination of damaged or unnecessary cells, but in cancers, the mechanisms of this pathway are deactivated, often through mutations in genes encoding proteins such as Bcl-2, Bax, or caspases (described in Section 2)." (PMID 40725141, 2025). "Another prominent effect of the azacitidine treatment was the significant suppression of BCL2, both at the mRNA and protein levels, which has previously been reported as a key mechanism underlying azacitidine-mediated cytotoxicity in various cancer cell lines (namely P39, HL60, and Jurkat)." (PMID 40728989, 2025). "A subfamily of Bcl-2, namely Bcl-2-like survival factors, acts as scavengers of pro-apoptotic proteins, performing anti-apoptotic functions, also Bcl-2 caused mild prevention for the inflammation-induced cancer." (PMID 38166099, 2024). "The suppression of Bcl-2 and induction of proapoptotic proteins by Gadd153 may increase the susceptibility of cancer cells to the mitochondria-dependent apoptotic pathway." (PMID 38473345, 2024). "c-Myc and Bcl-2 are key proteins regulating cell proliferation and survival, and abnormal alterations of associated genes are the most important biological features of cancer." (PMID 38410799, 2024).
cancer (continued). "Both overexpression and mutations affecting the anti-apoptotic protein BCL2 provide cancer cells with a survival advantage, leading the scientific and pharmaceutical communities to invest significant efforts into developing drugs specifically targeting this protein." (PMID 38670940, 2024). "An imbalance of protein BAX and BCL-2 expression may associate with the activation of the apoptosis process in cancer cells." (PMID 38499634, 2024). "The upregulation of Bcl-2 has been associated with many advancements in cancer research." (PMID 38978121, 2024). "Because loss of OXPHOS ETC increases BCL-2 dependence and the primed state of cancer cells, we explored whether mitochondria might operate as mechanistic amplifiers of the death signal delivered by cytolytic immune cells in FASNKO cells." (PMID 39349429, 2024). "Similarly, Bcl-2 reduction has been achieved by packing EVs with therapeutic biomolecules such as silencing RNA (bcl-2 siRNA) and antisense oligonucleotides (ASOs), or by stripping EVs of cancer-causing circular RNA (circRNA)." (PMID 39123496, 2024). "We comprehensively investigated cancer-associated somatic mutations affecting the transmembrane domain of BCL2 proteins and elucidated their effect on membrane insertion, hetero-interactions with the pro-apoptotic protein BAX, and modulation of cell death in cancer cells." (PMID 38670940, 2024). "Furthermore, cancer-associated somatic mutations in BCL2 genes interfere with the protein interaction network, thereby promoting cell survival." (PMID 38670940, 2024). "These efforts could contribute to innovative therapeutic interventions targeting Bcl-2-associated pathways in cancer." (PMID 39840282, 2024). "The observed decreased concentration of BCL-2 may be associated with a reduced ability of cells to inhibit apoptosis (programmed cell death), and this could potentially make cancer cells more susceptible to cell death." (PMID 38926453, 2024). "Bcl-2, a known anti-apoptotic agent, has been associated with the advancement of cancer." (PMID 38978121, 2024). "Overall, our results contribute to BCL2 mutational studies with additional experimental data about protein behavior with regard to cancer cell survival and provide new insight to guide decisions for optimal patient treatment, distinguishing driver mutations from passenger mutations." (PMID 38670940, 2024). "In conclusion, these results demonstrate that cancer-associated mutations in the BCL2 TMD may affect BCL2 functionality and contribute to the regulation of cell death." (PMID 38670940, 2024). "Interestingly, other studies have described metabolic changes associated with resistance to BCL-2 inhibition in other cancer models, consistent with our findings in BCP-ALL cells." (PMID 38961053, 2024). "Treatments that specifically target genetic variants or protein interactions linked to Bcl-2 SNPs may be able to return cancer cells to normal apoptotic pathways, which would ultimately result in their elimination." (PMID 39840282, 2024). "We focus on one of our particular candidates, BCL-2, that has compelling cancer associations." (PMID 38062391, 2023). "In contrast, the results of several papers included in this study, the upregulation of Bax expression and the downregulation of Bcl-2 expression demonstrate that aconitine can promote the expression of apoptotic genes and cause excessive autophagy in cancer cells, which leads to apoptosis." (PMID 37180714, 2023).
cancer (continued). "In contrast, the over-activation of Bcl-2 and its anti-apoptotic effects is associated with the occurrence, progression, and prognosis of cancer and contributes to the promotion of the radiation and chemical resistance of various malignant tumors." (PMID 37263638, 2023). "The upregulation of anti-apoptotic Bcl-2 proteins and the loss of Bax and/or Bak are the predominant methods of evasion and represent several mechanisms of resistance to the apoptotic stimuli of some anti-cancer drugs." (PMID 36836619, 2023). "Since the pro-survival BCL-2 proteins are involved in such a broad range of cancers and intervention with a BH3 mimetic would cause those cells to undergo programmed cell death, therapeutics targeting the pro-survival BCL-3’s hydrophobic groove with small molecule compounds as BH3 mimetics." (PMID 36795726, 2023). "However, venetoclax resistance in cancer cells has already emerged due to acquired mutations in BCL-2 and upregulation of BCL-XL or MCL-1." (PMID 37684238, 2023). "ALA also successfully induces cancer cell death by increasing the expression of proapoptotic genes such as Bcl-2-associated X protein (Bax) and decreasing the expression of the primary antiapoptotic gene, B-cell lymphoma 2 (Bcl2)." (PMID 37496822, 2023). "Similarly, 17 caused cancer cell death by intrinsic apoptosis in all tested cell lines through the downregulation of Bcl-2 and upregulation of the cytochrome C protein expression." (PMID 37376026, 2023). "B-cell lymphoma 2 (BCL-2) is an antiapoptotic protein that also plays an important role in the intrinsic apoptosis pathway, and its dysregulation has been linked with the chemoresistance of many cancers by blocking drug-induced apoptosis." (PMID 37593172, 2023). "In some cancers, cisplatin resistance is caused by the overexpression of anti-apoptotic Bcl-2." (PMID 37104009, 2023). "Additionally, it has been reported to interact with BCL2, which is a well‐known inhibitor of apoptosis, and have been linked to more aggressive and high‐grade cancers." (PMID 36819185, 2023). "Cancer cells can develop resistance to apoptosis via mutation or modulating the expression of proapoptotic proteins, including Bax, or by inducing anti-apoptotic protein expression, such as Bcl-2." (PMID 36770806, 2023). "Bcl-2 promotes cell survival, and its overexpression is associated with cancer." (PMID 37324453, 2023). "Western blot analysis revealed that enhanced Bax expression and impaired Bcl-2 expression caused by circ_0000285 silencing in SK-N-BE and SK-N-SH cells suggested that circ_0000285 knockdown induced cancer cell apoptosis, but circ_0000285 overexpression showed the opposite effect." (PMID 37465351, 2023). "BHRF1 leads to increased anti-apoptotic gene expression such as of bcl2 which may cause genomic instability and progress into cancer cells." (PMID 37736518, 2023). "VDAC1 associating with Bcl-2, Bcl-xL or hexokinase prevents apoptosis in cancer cells." (PMID 36330491, 2022). "The proto-oncogene BCL2 is a blocker of apoptosis and mutations in the BCL2 gene lead to cancer." (PMID 35281111, 2022). "Deletions or inactivating mutations of Bax or Bak are uncommon, but many cancers that are resistant to treatment, including leukemia, gastric, and colon cancers, can demonstrate increased expression of pro-survival molecules such as Bcl-2 and Bcl-xL." (PMID 36185861, 2022). "Genistein also induced apoptosis in human cancer cells by triggering both caspase-3 and caspase-9 activity, causing cell death by inhibiting NF-κB signaling and altering levels of the antiapoptotic protein Bcl-2 and proapoptotic protein." (PMID 35630647, 2022). "In addition to Bcl-2, upregulation of anti-apoptotic Bcl-xL is also common in various cancers and is associated with resistance to therapeutics." (PMID 35056993, 2022). "Indeed, in multiple studies, an elevated level of BCL2 was linked to cancer cells acquiring resistance to various chemotherapeutic molecules." (PMID 36361596, 2022).